ELK1 (ETS transcription factor ELK1)
Diseases named in the same sentence as ELK1 in open-access papers (continued):
Sharing a sentence is not in itself a finding about the gene and the disease.
cervical carcinoma (continued). "We also found that silencing ELK1 through siRNA inhibited the progression of the cervical cell cycle, proliferation, migration, and invasion, and inhibited cervical cancer cell apoptosis." (PMID 28544557, 2017). "In short, this study indicated that TCONS_00026907 was upregulated in cervical cancer and TCONS_00026907 promoted the progression of cervical cancer through inhibition of miR‐143‐5p and promotion of ELK1." (PMID 28544557, 2017). "Our study identifies TCONS_00026907 as a potent proto‐oncogene and indicates that TCONS_00026907/miR143‐5p/ELK1 regulatory pathway plays an important role in cervical cancer." (PMID 28544557, 2017). "Pharmaceuticals targeting ELK1 in gastric, head, neck, nasopharyngeal, liver, and cervical cancer." (PMID 40862737, 2025). "Given the fact that a similar mechanism, and both micro-RNAs, have been has been recorded in cervical cancer as well, hsa_circRPPH1_015 and ssa_circRNA_000166 were recognized as oncogenes, facilitating the dysregulation of ELK1 and leading to more aggressive phenotypes." (PMID 40862737, 2025). "Inhibition of ELK1 inhibited cell cycle entry and promoted apoptosis in cervical cancer." (PMID 31772143, 2019). "Furthermore, enhancement of ELK1 expression resulted in enhanced proliferation and invasion but repressed apoptosis and autophagy of cervical cancer cells." (PMID 31772143, 2019). "In addition, ELK1 has been found serve as an oncogene regulated by miRNAs to promote tumour progression in various human cancers, such as miR-326-ELK1 or miR-330-5p-ELK1 in cervical cancer, miR-2682-5p-ELK1 in bladder cancer, and miR-597-5p-ELK1 in pancreatic cancer." (PMID 35123530, 2022). "Meanwhile, ELK1 expression was higher in cervical cancer cells transfected with miR-326 inhibitor in the presence of si-hsa_circ_0000515, relative to those in the absence of si-hsa_circ_0000515, suggesting that hsa_circ_0000515 could upregulate ELK1 expression by repressing miR-326." (PMID 31772143, 2019). "Therefore, we speculated that lncRNA‐TCONS_00026907, which can serve as a competing endogenous RNA (ceRNA), is involved in the progression and prognosis of cervical cancer though the inhibition of miR‐143‐5p and the promotion of ELK1." (PMID 28544557, 2017). "However, the role of ELK1 in cervical cancer has yet to be studied." (PMID 28544557, 2017). "Furthermore, we confirmed that miR‐143‐5p inhibited the progression of the cervical cell cycle, proliferation, migration, and invasion, and inhibited cervical cancer cell apoptosis through downregulation of the protein expression levels of ELK1, p‐ELK1, C‐fos, Cyclin D1, and Bcl‐2." (PMID 28544557, 2017). "Research has pointed out that the ELK1-activated GPC3-AS1/GPC3 axis promotes the proliferation and migration of cervical cancer cells." (PMID 36814956, 2023). "Moreover, cervical cancer cells treated with miR-326 inhibitor exhibited increased ELK1 expression relative to those with inhibitor NC, suggesting that miR-326 could repress the expression of ELK1." (PMID 31772143, 2019). "Therefore, we speculated that hsa_circ_0000515, miR-326 and ELK1 were involved in cervical cancer." (PMID 31772143, 2019). "Our results indicate that H-rev107 was co-precipitated with H-RAS and downregulated the levels of activated RAS (RAS-GTP) and ELK1-mediated transactivation in epidermal growth factor-stimulated and H-RAS-cotransfected HtTA cervical cancer cells." (PMID 24884338, 2014). "LncRNA GPC3-AS1 and its nearby gene GPC3 are significantly upregulated in cervical cancer (CC) cells compared with normal cells; GPC3-AS1 and GPC3 synergistically enhance the proliferation and migration of CC cells by activating ELK1, thereby promoting CC development." (PMID 37965271, 2023). "No obvious change was observed in cervical cancer cells in response to hsa_circ_0000515 silencing and ELK1-over-expression." (PMID 31772143, 2019).
cervical carcinoma (continued). "Moreover, other transcriptional factors, such as Elk1 and Ets1, have been reported to control CIP2A gene expression in cervical cancer, endometrial carcinoma, and triple‐negative breast cancer." (PMID 30063110, 2018).
prostate carcinoma (28 papers, 2010 to 2025). A carcinoma that arises from epithelial cells of the prostate gland. "ELK-1 protein is known to be a critical partner for the androgen receptor (AR) in prostate cancer, and its expression was found to be associated with a higher clinical stage and prognostic marker of disease recurrence in prostate cancer." (PMID 33671331, 2021). "Recently, transcription factor Elk-1 which belongs to Ets family of transcription factors has been shown to be associated with prostate cancer progression." (PMID 29795364, 2018). "Elk1 has recently been discovered to play important roles in the progression of many cancer types, including the aggressiveness of pancreatic and prostate cancer." (PMID 40699751, 2025). "In prostate cancer (PCa), ELK1 has been credited with pivotal roles regarding tumorigenesis, tumor progression, and metastasis." (PMID 40862737, 2025). "Collectively, our studies demonstrate that AR knockdown improves the DTX sensitivity of prostate cancer cells by downregulating FEN1 through the ERK/ELK1 signalling pathway." (PMID 37326412, 2023). "Stimulation of prostate tissues with EPAC activators activated the transcription factor Elk1, a novel finding and important given that in prostate cancer cells Elk1 affects proliferation." (PMID 37830741, 2023). "We found that glucosamine, a metabolite produced by CAFs, induced high GlcNAcylation, which in turn induced Elk1-mediated transcription of 3βHSD1 in prostate cancer cells." (PMID 37009898, 2023). "Our findings suggest that CAF-secreted glucosamine increases GlcNAcylation in prostate cancer cells, promoting Elk1-induced HSD3B1 transcription, which upregulates de novo intratumoral androgen synthesis to overcome castration." (PMID 37009898, 2023). "To further explore the pathological roles of ELK1 in prostate cancer, we constructed ELK1 overexpression prostate cancer cells by transfection with pCMV-ELK1." (PMID 36439881, 2022). "ELK1-overexpression promoted cell proliferation and colony-forming ability of prostate cancer cells." (PMID 36439881, 2022). "Our data demonstrated that overexpression of ELK1 in prostate cancer cells contributed to the transcriptional activation of YTHDF1, further resulting in aberrant regulation of PLK1/PI3K/AKT axis." (PMID 36439881, 2022). "To further elucidate the role of ELK1 in prostate cancer, we investigate ELK1 expression by analyzing TCGA database." (PMID 36439881, 2022). "Result showed that ELK1 was upregulated in prostate cancer in cancer tissue compared with normal prostate tissue, and a significant increase was also observed in prostate cancer compared to paired normal prostate tissue." (PMID 36439881, 2022). "MED19 promotes androgen-independent growth by working with a transcription factor that interacts with AR, called ELK1, to induce the expression of genes regulated by AR that promote prostate cancer growth." (PMID 33513133, 2021). "Inhibition of ELK1 reduces expression of AR target genes and suppresses prostate cancer cell growth." (PMID 33513133, 2021). "The functional interactions between ELK1 and AR signaling pathways have been documented in prostate cancer cells." (PMID 29518027, 2018). "Since then, genome-wide studies have inferred potential regulatory cooperativity between AP1 and other ETS factors such as ELK1 and ERG and in the latter case this association is thought to be important for the context of prostate cancer." (PMID 28859074, 2017). "The abnormal activation of ELK1 played an important role in the malignant transformation of prostate cancer." (PMID 29158991, 2017). "We have previously demonstrated that ELK1 is necessary for androgen/AR-dependent growth of prostate cancer cells." (PMID 27793987, 2016). "We observed similar findings in prostate cancer lines: ELK1-shRNA strongly inhibited AR-negative cell migration/invasion and MMP-2/MMP-9 expression (unpublished data)." (PMID 26342199, 2015).
prostate carcinoma (continued). "In prostate cancer, ELK1-shRNA expression resulted in a significant decrease in the growth of androgen-sensitive/AR-positive LNCaP cells cultured with R1881, but not in that of LNCaP cultured without androgens or that of AR-negative cells." (PMID 26342199, 2015). "Recently, in prostate cancer cells where the role of AR signals had been extensively studied, AR was found to function as a coactivator of ELK1." (PMID 26342199, 2015). "Instead, in prostate cancer cells, AR was shown to function as a co-activator of ELK1 via bypassing the classical mechanism of ELK1 activation by phosphorylation." (PMID 26342199, 2015). "Amongst others, ELK1 is one of the key effectors of p38 signaling and regulates genes involved in migration, invasion, and metastasis in prostate cancer." (PMID 25504435, 2014). "The Elk-1 is required for androgen-receptor-dependent growth and the survival of prostate cancer cells." (PMID 25326651, 2014). "PTL was found to be particularly cytotoxic to prostatic cancer stem cells (or tumor-initiating cells, TICs), thus underscoring ELK1’s role in early PCa tumorigenesis and how its targeting may be a potential approach." (PMID 40862737, 2025). "We confirmed the regulatory effect of AR on FEN1, pho‐ERK1/2 and pho‐ELK1 in prostate cancer cells." (PMID 37326412, 2023). "Taken together, these results indicate that AR knockdown may enhance the chemosensitivity of prostate cancer cells by downregulating FEN1 through the ERK/ELK1 signalling pathway." (PMID 37326412, 2023). "Moreover, YTHDF1 regulated prostate cancer growth and metastasis via increasing translational efficiency of polo-like kinase 1 (PLK1) in an m6A dependent manner, and the transcription of YTHDF1 was activated by the dysregulation of ELK1 in prostate cancer." (PMID 36439881, 2022). "Thus, our results demonstrated that YTHDF1 transcription was activated by aberrant ELK1 in prostate cancer." (PMID 36439881, 2022). "In addition, ELK1 directly bind to AR to upregulate a major subset of its target genes which is essential to prostate cancer cell growth and survival." (PMID 36439881, 2022). "Researchers have confirmed ELK1 is a strong independent predictor of prostate cancer recurrence." (PMID 34966781, 2021). "Moreover, ELK1 inactivation resulted in strong inhibition of the growth of bladder (and prostate) cancer cells only in the presence of an activated AR." (PMID 29518027, 2018). "To test whether prostate cancer cells that are dependent on AR-V7 also depend on ELK1, we used shRNA to deplete ELK1 in CWR22Rv1 cells, which depend on endogenous AR-V7." (PMID 27793987, 2016). "Androgens could also activate a variety of target genes in ELK1-dependent manners and enhanced ELK1 promoter activity in prostate cancer cells." (PMID 26342199, 2015). "Again, the interaction between AR and ELK1 signals has been studied in prostate cancer cells." (PMID 26342199, 2015). "Indeed, ELK1-shRNA modestly increased the cell growth of AR-positive prostate cancer as well as bladder cancer in androgen-depleted conditions." (PMID 26342199, 2015). "Indeed, significant growth retardation was seen in androgen-sensitive, AR-positive prostate cancer LNCaP cells expressing ELK1-short hairpin RNA (shRNA), compared with control cells, cultured in the presence of androgen." (PMID 26342199, 2015). "Interestingly, ELK1 is obligatory for androgen receptor-dependent growth and survival of prostate cancer cells." (PMID 25504435, 2014). "In prostate cancer cells, Elk1 is involved in proliferation and tumor growth." (PMID 23815815, 2013). "In cultured prostate cancer cells, androgen receptors and growth factors activate Elk1 as well." (PMID 23226423, 2012). "Cytoplasm location to p-Elk-1 and p-ATF-2 could be mutant form that present altered functions and may be associated with the prostate cancer development." (PMID 20078866, 2010).
prostate carcinoma (continued). "Furthermore, targeting Elk1 activity in prostate cancer may decrease intratumoral androgen synthesis to impede CRPC progression." (PMID 37009898, 2023). "In addition, ELK1 expression was enhanced in advanced prostate cancer." (PMID 36439881, 2022). "Moreover, upregulated ELK1 induced migration and invasion of prostate cancer cells." (PMID 36439881, 2022). "Finally, we demonstrated that ELK1 contributed to YTHDF1 overexpression in prostate cancer." (PMID 36439881, 2022). "Additionally, in high clinical stage prostate cancer, ELK-1, not TCF members ELK3 or ELK4, was found to be associated with disease recurrence." (PMID 33671331, 2021). "Indeed, the impact of USP17 on ELK-1 function may extend beyond its relationship with ERK, given the recent discovery of a physical and functional cooperation between ELK-1 and androgen receptor in advanced prostate cancer." (PMID 30854565, 2019). "Indeed, in prostate cancer cells, AR has been shown to function as a co-activator of ELK1." (PMID 29518027, 2018). "In conclusion, AR knockdown results in the inactivation of the ERK/ELK‐1 signalling pathway that, in turn, leads to the downregulation of FEN1 and improves the DTX sensitivity of prostate cancer cells." (PMID 37326412, 2023). "Phosphorylation of PXN activated ERK/ELK1 and increased the transcription of c-FOS and cyclin D1, which in turn facilitated the proliferation of prostate cancer cells." (PMID 36923874, 2023). "In particular, the ETS family member ELK1 was found to interact with the N-terminal domain (NTD) of AR and directly regulate its recruitment to chromatin in prostate cancer cells." (PMID 33513133, 2021). "ELK1 is an ETS transcription factor that controls AR transcriptional activity and promotes prostate cancer progression." (PMID 33513133, 2021). "This suggests that MED19 cooperates with ELK1 to regulate AR occupancy and H3K27 acetylation at MAOA, upregulating its expression and driving androgen independence in prostate cancer cells." (PMID 33513133, 2021). "ELK1 is an ETS transcription factor and AR co-regulator that promotes growth in prostate cancer cells and regulates ligand-independent recruitment of AR to chromatin through interaction with the AR NTD." (PMID 33513133, 2021). "Endogenous ELK-1 and USP17 also co-immunoprecipitated from DU145 prostate cancer cells, in which USP17 expression is elevated." (PMID 30854565, 2019). "Their role in prostate cancer, especially in the case of Elk1, has not been fully uncovered; however, it is known that Elk1 and AR signaling have significant interplay." (PMID 40699751, 2025). "Although some articles reported that ELK1 regulated AR transcription and thus affected the progression of AR-positive prostate cancer cells 29, the role of ELK1 in AR-negative prostate cancer have not been fully elucidated." (PMID 36439881, 2022). "In addition, ChIP-qPCR assays suggested that ELK1 directly bound to the binding site 1 and 2 of YTHDF1 promoter region in prostate cancer cells." (PMID 36439881, 2022). "ELK1, as a transcriptional activator involved in the MAPK/ERK pathway, induces the proliferation and/or migration/invasion of bladder and prostate cancer cells as well as resistance to the cytotoxic effects of the chemotherapeutic agent cisplatin in bladder cancer cells." (PMID 34966781, 2021). "Because ELK1 in the ETS family has been reported to transactivate the CITED2 gene, we examined which member in the ETS family is responsible for CITED2 gene activation in prostate cancer." (PMID 30291252, 2018). "In prostate cancer (PCa) cells the androgen receptor (AR) is recruited by ELK1, via its amino-terminal domain (A/B), as a transcriptional co-activator, without ELK1 hyper-phosphorylation." (PMID 27793987, 2016).
prostate carcinoma (continued). "Nuclear paxillin has also been observed to increase cell proliferation via transcription of Cyclin D1 in prostate cancer cells, by acting as a nuclear scaffold, to promote extracellular-regulated kinase (ERK) phosphorylation of the ETS domain-containing protein (Elk-1)." (PMID 26984511, 2016). "For instance, androgens induced the expression of ELK1 and its downstream target c-fos in bladder cancer cells, while they failed to alter their expression significantly in prostate cancer cells." (PMID 26342199, 2015). "Similar to non-malignant conditions, Elk1 activation in prostate cancer cells is involved in proliferation and tumor growth." (PMID 23226423, 2012). "It has been demonstrated that ELK1-shRNA expression in LNCaP prostate cancer cells does not decrease, rather does increase modestly, their proliferation in an androgen depleted condition and that androgen does not significantly induce the proliferation of LNCaP-ELK1-shRNA cells." (PMID 26342199, 2015). "However, novel regulatory mechanism of ELK1 in prostate cancer was not fully elucidated." (PMID 36439881, 2022). "The authors also confirmed that in other cell types (human gastric and prostate cancer cells), the same TFs exhibit differential results regarding CIP2A expression, since ETS1 downregulation (without ELK1 silencing) was adequate to decrease CIP2A." (PMID 40862737, 2025). "In the presence of androgens, the most enriched motif corresponded not to ELK1 but to SP1, an AR-interacting protein upregulated in prostate cancer." (PMID 33513133, 2021).